PEX5 (peroxisomal biogenesis factor 5)
Description:
Receptor that mediates peroxisomal import of proteins containing a C-terminal PTS1-type tripeptide peroxisomal targeting signal (SKL-type). Binds to cargo proteins containing a PTS1 peroxisomal targeting signal in the cytosol, and translocates them into the peroxisome matrix by passing through the PEX13-PEX14 docking complex along with cargo proteins. PEX5 receptor is then retrotranslocated into the cytosol, leading to release of bound cargo in the peroxisome matrix, and reset for a subsequent peroxisome import cycle. [Isoform 1]: In addition to promoting peroxisomal translocation of proteins containing a PTS1 peroxisomal targeting signal, mediates peroxisomal import of proteins containing a C-terminal PTS2-type peroxisomal targeting signal via its interaction with PEX7. Interaction with PEX7 only takes place when PEX7 is associated with cargo proteins containing a PTS2 peroxisomal targeting signal. PEX7 along with PTS2-containing cargo proteins are then translocated through the PEX13-PEX14 docking complex together with PEX5. [Isoform 2]: Does not mediate translocation of peroxisomal import of proteins containing a C-terminal PTS2-type peroxisomal targeting signal.
Synonyms: PTS1R; PXR1; PBD2A; PBD2B; PTS1-BP; RCDP5
Tractability: Small molecule: it has a high-quality binding pocket. PROTAC: UniProt records ubiquitination sites on it; ubiquitination databases record sites on it; its protein half-life has been measured.
Gene: Protein-coding gene on chromosome 12 (7,188,653 to 7,218,574, forward strand). Ensembl gene ENSG00000139197.
Subcellular location: Cytoplasm, cytosol; Peroxisome matrix
Subcellular location (Human Protein Atlas): Cytosol; Golgi apparatus
Pathways (Reactome):
Autophagy: Pexophagy
Metabolism of proteins: E3 ubiquitin ligases ubiquitinate target proteins
Protein localization: Peroxisomal protein import
Gene Ontology:
Molecular function: enzyme binding; peroxisome targeting sequence binding; protein binding; protein carrier chaperone; small GTPase binding; protein-macromolecule adaptor activity
Biological process: cellular response to reactive oxygen species; negative regulation of protein-containing complex assembly; pexophagy; protein import into peroxisome matrix; protein import into peroxisome matrix, docking; protein import into peroxisome matrix, receptor recycling; protein import into peroxisome matrix, substrate release; protein import into peroxisome membrane; protein import into peroxisome matrix, translocation
Cellular component: cytoplasm; cytosol; Golgi apparatus; membrane; peroxisomal matrix; peroxisomal membrane; peroxisome; protein-containing complex
Genetic constraint (gnomAD): Loss-of-function variants: 48 observed, 79.45 expected, observed/expected ratio (o/e) 0.6, 90% interval 0.48 to 0.77. The upper end of that interval is the gene's LOEUF score, 0.77, which puts it in group 3 of 6, group 1 being the genes least tolerant of losing a copy. Missense variants: 677 observed, 820.17 expected, observed/expected ratio (o/e) 0.83, 90% interval 0.77 to 0.88. Synonymous variants: 290 observed, 326.53 expected, observed/expected ratio (o/e) 0.89, 90% interval 0.81 to 0.98.
Gene-disease validity (ClinGen):
ClinGen rates the evidence that PEX5 causes each of these diseases.
peroxisome biogenesis disorder (autosomal recessive): Definitive.
Homologues: Orthologues: chimpanzee PEX5 (99% identical), macaque PEX5 (99% identical), pig PEX5 (97% identical), rabbit PEX5 (97% identical), rat Pex5 (95% identical), mouse Pex5 (94% identical), dog PEX5 (92% identical), guinea pig PEX5 (77% identical), tropical clawed frog pex5 (65% identical), zebrafish pex5 (58% identical), Drosophila melanogaster Pex5 (35% identical), Caenorhabditis elegans prx-5 (26% identical). Paralogues in human: PEX5L (37% identical).
Diseases named in the same sentence as PEX5 in open-access papers:
PEX5 is named in the same sentence as 43 diseases in open-access papers, as found by Europe PMC text mining. Sharing a sentence is not in itself a finding about the gene and the disease. The quoted sentences say what the papers report.
Zellweger syndrome (14 papers, 2016 to 2025). "Mice with homozygous Pex5 mutations (Pex5−/− mice) recapitulate the phenotype of Zellweger syndrome in humans." (PMID 36821008, 2023). "By altering the different parameters to recapitulate the peroxisomal phenotype seen in different pathologies, the model is also applicable to other disease conditions, e.g., the loss of PEX5 in Zellweger spectrum disorders." (PMID 35741050, 2022). "A cellular model of Zellweger syndrome, particularly of a Pex5 mutation, has shown an increase in alpha-synuclein Lewy bodies; alpha-synuclein is thought to be a causative agent in Parkinson disease, particularly in familial cases." (PMID 32210766, 2020). "Molecular testing ordered prior to her death identified two pathogenic variants in PEX5, consistent with the clinical diagnosis of Zellweger syndrome." (PMID 33239602, 2020). "The phenotype of mice with Pex2, Pex5 and Pex13 deficiency resembles the severe form of human Zellweger syndrome." (PMID 26686055, 2016). "Genetic deletion of Pex2, Pex5, or Pex13 in mice causes profound and global peroxisome deficiency, and is associated with growth delay, severe hypotonia, and death shortly after birth, similar to Zellweger syndrome in humans." (PMID 40949164, 2025). "Loss of PEX5 function (or of other peroxins of the peroxisomal matrix protein import machinery) causes Zellweger syndrome (ZS), a spectrum of peroxisome biogenesis disorders with severe developmental and neurological defects." (PMID 35741050, 2022). "Mitochondrial abnormalities are found in patients with Zellweger syndrome and mouse models with deletion of Pex2 and Pex5, underscoring the role of peroxisomes in mitochondrial health." (PMID 37338571, 2023). "Patients with Zellweger syndrome, due to the mutations in PEXs (e.g., PEX1 and PEX5), often develop severe hepatic dysfunction and show elevated inflammation." (PMID 32523050, 2020). "Currently, several mouse models of the Zellweger spectrum disorders are available, which are represented by mice with targeted deletions in the genes encoding the peroxins PEX2, PEX5 or PEX13." (PMID 26686055, 2016). "Zellweger spectrum disorders (ZSDs), including archetypal Zellweger syndrome, neonatal adrenoleukodystrophy (NALD) and infantile Refsum disease (IRD), are PBDs caused by mutations in peroxin genes (PEX1, PEX2, PEX3, PEX5, PEX6, PEX10, PEX11β, PEX12, PEX13, PEX14, PEX16, PEX19 or PEX26)." (PMID 40949164, 2025). "Accordingly, mutations in human PEX5 cause Zellweger spectrum disorders (ZSDs) in which functional peroxisomes are largely absent." (PMID 36821008, 2023). "In Zellweger syndrome, which is inherited in an autosomal recessive manner, one of 13 peroxin (PEX) genes is mutated (PEX1, PEX2, PEX3, PEX5, PEX6, PEX10, PEX11β, PEX12, PEX13, PEX14, PEX16, PEX19, PEX26), leading to issues with neuronal migration, myelination and brain development." (PMID 32210766, 2020).
peroxisome biogenesis disorder (8 papers, 2011 to 2025). "Mutations in PEX5, encoding the peroxisomal targeting signal 1 receptor, can cause peroxisomal biogenesis disorders of the Zellweger spectrum." (PMID 34356630, 2021). "Defects in PEX5 cause one of several peroxisome biogenesis disorders, accompanied by reduced plasmalogen biosynthesis in the brain." (PMID 21291537, 2011). "In contrast to other peroxisomal biogenesis disorder (PBD) mouse models (such as the Pex5, Pex2, Pex13 knockout mice), which mimic the Zellweger spectrum symptoms, the Pex11a knockout mice still contain peroxisomes that harbor the typical peroxisomal marker enzymes." (PMID 41511296, 2025). "RCDP is a recessive peroxisomal disease caused by variants in five genes: AGPS, FAR1, GNPAT, PEX5, and PEX7, which encode alkylglycerone phosphate synthase, fatty alcohol reductase 1, glycerone-phosphate O-acyltransferase, and the peroxisomal biogenesis factors 5 and 7, respectively." (PMID 40394457, 2025). "As in patients with mild peroxisome biogenesis disorders who develop regressive changes, demyelination in cerebellum and brain stem preceded major myelin loss in corpus callosum of both Nestin-Pex5−/− and CMV-Tx-Pex5−/− mice." (PMID 22458306, 2012).
Hepatic steatosis (3 papers, 2020 to 2025). Steatosis is a term used to denote lipid accumulation within hepatocytes. "Furthermore, a study using mice with liver-specific PEX5 knockouts revealed hepatic steatosis due to peroxisomal deficiency." (PMID 40943222, 2025). "Although hepatic steatosis is evident in liver-specific PEX5 knockout mice, the translational relevance to human peroxisomal disorders requires further establishment in human-based models." (PMID 40943222, 2025). "These mice developed hepatic steatosis similar to other models of loss of peroxisome function, such as in PEX2 and PEX5 deficiency." (PMID 37338571, 2023). "Consistently, it has been reported that liver-specific PEX5 deletion induces hepatic steatosis due to lipid accumulation, one of the symptoms of NLSD61." (PMID 31996685, 2020).
hepatocellular carcinoma (3 papers, 2020 to 2022). A malignant tumor that arises from hepatocytes. "In our previous work, PEX5 was found to be involved in radioresistance in hepatocellular carcinoma (HCC)." (PMID 34249928, 2021). "PEX5, a novel target of MIR31, is also proven to be a therapeutic option in hepatocellular carcinoma." (PMID 36590397, 2022). "However, based on the Integrative Molecular Database of Hepatocellular Carcinoma (HCCDB), we further found that the mRNA level of only PEX5 affected the overall survival of HCC patients." (PMID 32373215, 2020).
liver cancer (2 papers, 2020 to 2021). An epithelial or non-epithelial malignant neoplasm that arises from the liver. "Moreover, the upregulation of PEX5 in liver cancer cells was also found to be associated with radioresistance; however, whether PEX5 is a regulator of peroxisomal ferroptosis remains unclear." (PMID 34249928, 2021). "The Wnt/β-catenin signaling pathway is usually hyperactivated in liver cancers 41, consistent with our observations of decreased miR-31-5p and increased PEX5 levels in HCC." (PMID 32373215, 2020). "In the ONCOMINE datasets, PEX5 mRNA was upregulated at the advanced stage (Barcelona Clinic Liver Cancer stage) of HCC." (PMID 32373215, 2020).
rhizomelic chondrodysplasia punctata (2 papers, 2024 to 2025). Rhizomelic chondrodysplasia is a form chondrodysplasia punctata, a group of diseases in which the common characteristic is calcifications near joints at birth. "Thus, we next investigated primary human fibroblasts from a patient with RCDP-2 (rhizomelic chondrodysplasia punctata type-2) harboring mutations in the enzyme glyceronephosphate O-acyltransferase (GNPAT) required for ether phospholipid synthesis via a PTS1/Pex5-dependent mechanism." (PMID 38397481, 2024).
cardiac arrhythmia (1 paper, 2020). Any disturbances of the normal rhythmic beating of the heart or MYOCARDIAL CONTRACTION. "On the other hand, KD of the key factors (peroxines) involved in peroxisomal import process (Pex5, Pex1, and Pex14) in oenocytes significantly induced cardiac arrhythmia." (PMID 32523050, 2020). "KD of either upd3, or kay, or Jra specifically in oenocytes attenuated Pex5 KD-induced cardiac arrhythmia." (PMID 32523050, 2020). "To determine whether upd3 and JNK signaling are required for oenocyte PIS-induced cardiac dysfunction, we analyzed the genetic interaction between Pex5 and upd3 (or kay, Jra) in nonautonomous regulation of cardiac arrhythmia." (PMID 32523050, 2020). "Interestingly, unlike oenocyte-specific manipulation, knocking down of Pex5 in FB and gut using S106GS-Gal4 did not induce cardiac arrhythmia." (PMID 32523050, 2020).
cardiomyopathy (1 paper, 2020). A disease of the heart muscle or myocardium proper. "Together, our data showed that preserving peroxisomal import function via overexpression of endogenous Pex5 can block the production of ROS and peroxikine upd3, and protect hearts from oxidative stress- and aging-induced cardiomyopathy." (PMID 32523050, 2020).
Cognitive impairment (1 paper, 2020). Abnormal cognition is characterized by deficits in thinking, reasoning, or remembering. "The involvement of peroxisomes in memory function was also suggested by CNS-specific Pex5 knockout (Nes-Pex5–/–) mouse that manifests the cognitive impairment." (PMID 33163488, 2020).
diabetes (1 paper, 2017). "Suppressed levels of peroxisomal biogenesis markers such as PMP70, catalase, and PEX5 in kidneys of STZ-induced diabetes mice were recovered by APX-115 or losartan." (PMID 29088780, 2017).
glioma (1 paper, 2024). A benign or malignant brain and spinal cord tumor that arises from glial cells (astrocytes, oligodendrocytes, ependymal cells). "Overall, our results suggest that a deficiency in the import of peroxisomal matrix proteins due to PEX5 knockout inhibits the cell growth, migration, and invasion of glioma cells." (PMID 38540734, 2024). "Our findings demonstrate that PEX5-dependent metabolic pathways are significantly involved in glioma development." (PMID 38540734, 2024). "We designed two sgRNAs to target the PEX5 gene and successfully knocked out (KO) PEX5 in glioma U251 cells, as confirmed by the Western blot analysis." (PMID 38540734, 2024). "In this study, we elucidate that PEX5 is indispensable for the cell growth, migration, and invasion of glioma cells." (PMID 38540734, 2024). "We developed a PEX5-dependent prognosis model and evaluated its sensitivity, specificity, and accuracy in predicting the survival of glioma patients." (PMID 38540734, 2024). "To examine the potential role of these immune cells in the prognosis value of the PEX5-dependent model, we computed the abundance of the three types of immune cells in each glioma patient through ssGSEA." (PMID 38540734, 2024). "This PEX5-dependent signature not only serves as a robust prognosis model capable of accurately predicting outcomes for glioma patients, but also effectively distinguishes several clinicopathological features, including the grade, isocitrate dehydrogenase (IDH) mutation, and 1p19q codeletion status." (PMID 38540734, 2024). "Furthermore, we knocked out the PEX5 gene and assessed the essentiality of PEX5 in glioma cell growth, migration, and invasion." (PMID 38540734, 2024). "The distinct roles exhibited by PEX5 and these signature genes could highlight the varied functions of PEX5 targets within different cell types present in the glioma tumor." (PMID 38540734, 2024). "Finally, our validation reveals that the elevated expression of GSTK1, an antioxidant enzyme within the signature, promotes the cell growth and migration of glioma cells, with this effect dependent on the peroxisomal targeting signal recognized by PEX5." (PMID 38540734, 2024). "Our PEX5-dependent prognosis model takes advantage of the unique peroxisomal metabolism and highlights the pivotal role of the PEX5-dependent peroxisomal metabolism in glioma development." (PMID 38540734, 2024). "Notably, our results indicate that PEX5 promotes the cellular growth, migration, and invasion of glioma cells." (PMID 38540734, 2024). "Therefore, we investigated whether the PTS1- or PTS2-containing metabolic enzymes, whose peroxisomal localization depends on PEX5, could be used to establish a prognostic model for glioma." (PMID 38540734, 2024).
Hyperoxaluria (1 paper, 2024). Increased excretion of oxalates in the urine. "It has been associated with hyperoxaluria with NL and NC with variants in PEX1 and PEX3, likely with variants in PEX5, and possibly with variants in PEX6, PEX7, PEX10, PEX11, PEX12, PEX13, PEX16, and PEX26." (PMID 38606357, 2024). "It has been associated with hyperoxaluria with NL and NC with variants in PEX1, likely with variants in PEX5, and possibly with variants in PEX3, PEX6, PEX 10, PEX 12, PEX13, PEX14, PEX16, PEX19, and PEX26." (PMID 38606357, 2024).
hypothyroidism (1 paper, 2021). Abnormally low levels of thyroid hormone. "In contrast, Pex5(S) protein expression was stable at day 7 but increased on day 15 of hypothyroidism and remained increased." (PMID 34571897, 2021). "Hence, our results suggest that early hypothyroidism favors import of PTS1 proteins, but since they are more numerous than PTS2 this trend continues until the end of the treatment, through Pex5(S) activity." (PMID 34571897, 2021).
Obesity (1 paper, 2024). Accumulation of substantial excess body fat. "However, with obesity, we observed increased accessibility of genes involved in cell cycle regulation (ATM, CDKN1C, BCL2L11), autophagy (HSPA8, IRF8, PEX5), and protein catabolism (CDC34, CTSB, UBB)." (PMID 39872537, 2024).
parasitic diseases (1 paper, 2021). "Perturbation of this molecule and its interacting protein PEX-5 results in shortened lifespan and even lethality in H. contortus, suggesting novel potential targets for the control of parasitic diseases of socioeconomical significance." (PMID 34270617, 2021).
prostate carcinoma (1 paper, 2024). A carcinoma that arises from epithelial cells of the prostate gland. "PC3-LN4 prostate cancer cells lacking PIM1, which display higher GSK3β activation, show a significant decrease in genes linked to peroxisomal biogenesis (peroxisomal biogenesis factor 3 and 5; PEX3 and PEX5) and LD growth (Tip47)." (PMID 38097734, 2024).
Renal cyst (1 paper, 2022). A fluid filled sac in the kidney. "No cortical renal cysts were found in the kidney of Pex5-null mice at P0.5, but retardation in the intrauterine maturation of glomeruli was observed." (PMID 35191396, 2022).
steatosis (1 paper, 2024). Increased lipid within the cytoplasm of cells. "Clofibrate significantly inhibited HFD-induced steatosis, increasing p62-, LAMP2-, and Pex5-positive granules by 7.5-, 7.2-, and 71.4-fold, respectively, while decreasing NBR1 expression." (PMID 39765694, 2024). "The results suggest that steatosis was completely suppressed through peroxisome activation; however, an imbalance between the induction and inhibition of pexophagy was demonstrated by increased levels of p62, LAMP2, and Pex5." (PMID 39765694, 2024).
Tetralogy of Fallot (1 paper, 2017). A congenital cardiac malformation comprising pulmonary stenosis, overriding aorta, ventricular septum defect, and right ventricular hypertrophy. "Our findings identify PEX5, NACA, ATXN2, CELA1, PCDHB4 and CTBP1 mutations as underlying genetic causes of isolated tetralogy of Fallot." (PMID 29291004, 2017). "Analysis using Gene Ontology /pathway, Online Mendelian Inheritance in Man, PubMed and other databases revealed that PEX5, NACA, ATXN2, CELA1, PCDHB4 and CTBP1 were associated with Tetralogy of Fallot." (PMID 29291004, 2017).
trypanosomiasis (1 paper, 2022). Infection with protozoa of the genus trypanosoma. "This study identifies small molecule inhibitors of PEX5 interaction with the cargo and validates PEX5 as a relevant target in trypanosomiasis paving the road to future development of pharmacologically relevant small molecules." (PMID 36038611, 2022).